BTK (Bruton tyrosine kinase)
Diseases named in the same sentence as BTK in open-access papers (continued):
Sharing a sentence is not in itself a finding about the gene and the disease.
Stroke (4 papers, 2015 to 2025). Sudden impairment of blood flow to a part of the brain due to occlusion or rupture of an artery to the brain. "Evobrutinib inhibits the expression and activation of BTK in microglia, reducing M1 microglia-mediated neuroinflammation and alleviating ischemic injury following stroke." (PMID 40263985, 2025). "As a potential therapeutic target, more comprehensive research on the roles and mechanisms of BTK and BTK inhibitors in stroke is warranted in the future to provide new insights and strategies for clinical stroke treatment." (PMID 40263985, 2025). "To determine the therapeutic time window, we examined the effect of BTK inhibitor administration 12 and 24 h after stroke onset." (PMID 26059659, 2015). "The expression of BTK and inflammasome in the ischaemic brain was measured on day 1 after stroke onset." (PMID 26059659, 2015). "Since CNS microglia are the primary cells expressing BTK, Evobrutinib, which targets microglial BTK, may offer neuroprotective effects post-stroke." (PMID 40263985, 2025). "Protective role of B cells in inflammation also suggests a limitation of the application of BTK inhibitors for inflammatory diseases; however, if BTK inhibitors are used only during the acute phase of stroke, effects on B cells may be negligible." (PMID 26059659, 2015).
Alzheimer disease (3 papers, 2019 to 2025). A progressive, neurodegenerative disease characterized by loss of function and death of nerve cells in several areas of the brain leading to loss of cognitive function such as memory and language. "BTK was involved in regulating microglial phagocytosis and the uptake of synaptic structures in Alzheimer’s disease." (PMID 38129902, 2023).
anemia (3 papers, 2022 to 2025). A reduction in the number of red blood cells, the amount of hemoglobin, and/or the volume of packed red blood cells. "The other four included a 69 year old female with CLL and a history of COVID-19 in December, 2020, a 71 year old male with cirrhosis, a 79 year old female with CLL on BTK inhibitor and prior anti-CD20 antibody x years before and a 64 year old male with mild renal insufficiency and anemia." (PMID 36405515, 2022).
Crohn disease (3 papers, 2020 to 2022). A gastrointestinal disorder characterized by chronic inflammation involving all layers of the intestinal wall, noncaseating granulomas affecting the intestinal wall and regional lymph nodes, and transmural fibrosis. "A negative role of BTK in NLRP3 inflammasome activation is also supported by the evidence that Btk–/– mice exhibit increased severity of TNBS-induced colitis due to elevated IL-1β production, which may partially explain why XLA patients are prone to develop Crohn’s disease." (PMID 34485307, 2021).
diabetes (3 papers, 2021 to 2022). "We have shown that inhibition of macrophage BTK reduces cytokine and chemokine release both in vitro and in vivo in diabetes and poly microbial sepsis." (PMID 34897650, 2022). "However, it remained unclear whether BTK inhibition has remedial effects on ischemia/reperfusion (I/R) injury complicated with diabetes." (PMID 34605340, 2021).
experimental autoimmune encephalomyelitis (3 papers, 2015 to 2025). An autoimmune demyelinating disease of the central nervous system that is produced experimentally in animals by the injection of homogenized brain or spinal cord in Freund's adjuvant. "Here we demonstrate efficacy of BTK inhibition in a model of secondary progressive autoimmune demyelination in Biozzi mice with experimental autoimmune encephalomyelitis (EAE)." (PMID 37438842, 2023).
heart failure (3 papers, 2023 to 2024). Inability of the heart to pump blood at an adequate rate to meet tissue metabolic requirements. "The Bruton tyrosine kinase (BTK) inhibitor Ibrutinib is associated with a higher incidence of cardiotoxic side effects including heart failure (HF)." (PMID 37655217, 2023).
immune thrombocytopenia (3 papers, 2021 to 2024). "The activation of macrophages and monocytes via cross-linking of IgG and FcgR is a BTK dependent function; the ability of rilzabrutinib to prevent IgG mediated FcgR activation was illustrated in rodent models of lupus nephritis and immune thrombocytopenia (ITP)." (PMID 34447768, 2021). "Rilzabrutinib, a reversible covalent Bruton’s tyrosine kinase (BTK) inhibitor, has promising potential in immune thrombocytopenia." (PMID 38791529, 2024).
liver fibrosis (3 papers, 2020 to 2024). "In addition, previous studies indicate that ibrutinib, a first-generation small molecule inhibitor of BTK, has an anti-fibrotic effect in multiple organ fibrosis diseases, containing tumor fibrosis, liver fibrosis, and chronic pancreatitis." (PMID 37630287, 2023).
mast cell tumor (3 papers, 2019 to 2022). "In canine mast cell tumors, Ibrutinib, a BTK inhibitor, can inhibit IgE-dependent activation and histamine release in mast cells." (PMID 36069808, 2022). "The aim of this study was to investigate whether BTK serves as a novel therapeutic target in canine mast cell tumours (MCTs)." (PMID 31286638, 2019).
mastitis (3 papers, 2020 to 2024). Inflammation of breast tissue during lactation or postpartum due to an obstructed duct or infection. "CmCGG DMEGs like IL6R, TNF, BTK, IL1R2, and TNFSF8 enriched in several immune-related GO terms and pathways indicated their important roles in host immune response and their potential as candidate genes for S. aureus mastitis." (PMID 33193625, 2020). "Moreover, genome-wide DNA methylation alteration in the format of CmCGG was significantly related to the immune response to S. aureus-induced mastitis, and several genes including IL-6R, TNF, BTK, IL-1R2, and TNFSF8 were identified as potential epigenetic markers of S. aureus mastitis." (PMID 33708235, 2020).
nephritis (3 papers, 2016 to 2022). Inflammation of renal tissue. "Our results highlight the important role for BTK in the pathogenesis of immune complex-mediated nephritis, and BTK inhibition as a promising therapeutic target for LN." (PMID 27192942, 2016). "Hence, we also examined the therapeutic efficacy of BTK inhibition on anti-GBM nephritis." (PMID 35874767, 2022).
neuromyelitis optica spectrum disorders (3 papers, 2022 to 2025). "Indeed, BTK inhibition dampens microgliosis in LPS-induced neuroinflammation and chronic white matter ischemia and enhances microglial phagocytosis while reducing microglial TNF-α in vivo in the animal model of neuromyelitis optica." (PMID 40607415, 2025).
sarcoma (3 papers, 2024 to 2025). A usually aggressive malignant neoplasm of the soft tissue or bone. "Prolonged exposure to kinase inhibitors such as BTK inhibitors as seen in the MCL case morphed into sarcoma, could certainly be a factor promoting BCR/BTK independence including transdifferentiation and a related profound cell-signaling reprograming, as a very drastic mechanism of drug resistance." (PMID 38638855, 2024).
T-cell lymphomas (3 papers, 2016 to 2021). "Only SYK was down-regulated (log2 fold-change −2.7) and BTK showed a borderline non-significant tendency towards down-regulation (log2 fold-change −2.0) in probable T-cell lymphomas." (PMID 29674676, 2018).
Tumor Lysis Syndrome (3 papers, 2021 to 2023). a group of metabolic abnormalities that can occur as a complication during the treatment of cancer, most commonly after the treatment of lymphomas and leukemias. "However, venetoclax requires tumour lysis syndrome (TLS) monitoring and leads to higher rates of FEN than treatment with BTK inhibitors." (PMID 33705648, 2021).
Anxiety (2 papers, 2020 to 2021). Intense feelings of nervousness, tension, or panic often arise in response to interpersonal stresses. "Stress leads to an exacerbated neuroinflammatory response and significantly more anxiety in female mice, and with both these BTK inhibitors the rescue in female animals were also more pronounced than in males." (PMID 34895246, 2021). "Therefore, we worked with the hypothesis that if BTK could be inhibited, then we would see a rescue from stress-induced anxiety with the reversal of the neuroinflammatory profile." (PMID 34895246, 2021).
apical periodontitis (2 papers, 2019 to 2025). "Previous studies have demonstrated elevated BTK expression in refractory periapical periodontitis, correlating with bone resorption and PD progression." (PMID 41221328, 2025). "Studies have shown that the Bruton tyrosine kinase- (Btk-) phospholipase Cγ2 (PLCγ2) signaling pathway plays an important role in bone absorption, but it is unknown whether it plays a role in apical periodontitis bone destruction." (PMID 31427888, 2019).
cardiac tamponade (2 papers, 2024 to 2026). Acute compression of the heart caused by increased intrapericardial pressure due to the collection of blood or fluid in the pericardium from rupture of the heart, penetrating trauma, or progressive effusion. "These three cases highlight the rare but potentially life-threatening risk of cardiac tamponade which can occur even with newer generations of BTK inhibitors." (PMID 39015770, 2024). "We report three cases of patients on BTK inhibitors who developed acute pericarditis and cardiac tamponade." (PMID 39015770, 2024). "Clinicians should maintain a high index of suspicion for cardiac tamponade in patients receiving BTK inhibitors who present with nonspecific cardiopulmonary symptoms." (PMID 41684975, 2026).
cellulitis (2 papers, 2023 to 2025). Inflammation of the dermis and subcutaneous tissues caused by a bacterial infection. "Ibrutinib and other BTK inhibitors are also known to cause various cutaneous manifestations, including cellulitis, neutrophilic dermatoses, ecthyma, lichenoid eruption, onychomadesis, paronychia, pyogenic granuloma (periungual), pityriasis rosacea, and pyoderma gangrenosum." (PMID 40416196, 2025).
cryoglobulinemia (2 papers, 2023 to 2024). Cryoglobulinemia is a type of vasculitis that is caused by abnormal proteins (antibodies) in the blood called 'cryoglobulins.' At cold temperatures, these proteins become solid or gel-like, which can block blood vessels and cause a variety of health problems. "Given the pathophysiology of cryoglobulinemia, it would be prudent to explore the efficacy of BTK inhibitors in the acute and chronic setting (to rapidly reduce IgM levels) for its treatment in WM." (PMID 39417016, 2024). "We initiated management of cryoglobulinemia with dexamethasone, rituximab, and cyclophosphamide; in Bing-Neel, bortezomib and dexamethasone, followed by a Bruton tyrosine kinase inhibitor." (PMID 37304326, 2023). "Our patient with BNS and cryoglobulinemia did not have an MYD88 mutation that would have conferred favorability towards BTK inhibitor treatment response and, thus, was instead treated with plasmapheresis and chemotherapy." (PMID 39417016, 2024).
DDON syndrome (2 papers, 2020 to 2025). "Large deletions involving BTK and adjacent genes, such as TIMM8A, cause syndromic forms, such as Mohr-Tranebjaerg syndrome, which includes neurodegeneration and hearing loss." (PMID 40863427, 2025). "Thus, it is important for clinicians to consider the possibility of a deletion of the last exon 19 in the BTK gene in patients suspected of having DDON syndrome, and to further test for the existence of the neighboring TIMM8A gene to allow for an effective therapeutic strategy." (PMID 33013854, 2020).
demyelinating disease (2 papers, 2024 to 2025). A broad group of disorders that affect the myelin sheaths that cover the neurons. "Tolebrutinib, an oral Bruton’s tyrosine kinase (BTK) inhibitor with blood–brain barrier penetration, exerts its therapeutic effects in demyelinating diseases through a dual-step mechanism." (PMID 41471322, 2025). "Furthermore, our data suggest that besides its dampening role in neuroinflammation, BTK inhibition is independently able to enhance repair and remyelination in demyelinating diseases, such as MS." (PMID 38656399, 2024).
endothelial dysfunction (2 papers, 2024 to 2025). In vascular diseases, endothelial dysfunction is a systemic pathological state of the endothelium (the inner lining of blood vessels) and can be broadly defined as an imbalance between vasodilating and vasoconstricting substances produced by (or acting on) the endothelium. "Evidence suggests that BTK inhibition leads to an imbalance between the oxidative and antioxidant systems, resulting in endothelial dysfunction that reduces vascular tone and enhances contraction." (PMID 40453665, 2025).
enteroviral infections (2 papers, 2018 to 2025). "In conclusion, selective impairment of type I and III IFN productions in response to OPV but not to H1N1 was demonstrated in XLA patients, implicating BTK-dependent impairments are responsible for the unique susceptibility of these patients to severe enterovirus infections." (PMID 30147693, 2018).
Erythema (2 papers, 2018 to 2024). Redness of the skin, caused by hyperemia of the capillaries in the lower layers of the skin. "Our cases exhibit the variability in disease course of localized extremity edema and erythema in the setting of BTK inhibitor therapy." (PMID 39687072, 2024). "Herein, we report 2 cases of individuals on BTK inhibitors with localized erythema over an extremity that progressed to severe pitting edema in one case." (PMID 39687072, 2024).
food allergies (2 papers, 2019 to 2023). "For example, one study is planning on looking at the oral janus kinase (JAK) inhibitor abrocitinib for food allergy (NCT05069831), while another is evaluating the efficacy of the Bruton's tyrosine kinase (BTK) inhibitor remibrutinib for the treatment of food allergy (NCT05432388)." (PMID 37520143, 2023).
granulomatosis with polyangiitis (2 papers, 2021). A small-vessel necrotizing vasculitis characterized by the association of inflammation of the vessel wall and peri- and extravascular granulomatosis. "In granulomatosis with polyangiitis (GPA) patients, BTK levels were increased in peripheral B cells of patients with active disease but not patients in remission, indicating its association with disease activity." (PMID 34150760, 2021).
Graves’ orbitopathy (2 papers, 2022 to 2024). "In this study, we investigated the therapeutic effect of ibrutinib, an orally bioavailable BTK inhibitor in the pathogenesis of Graves’ orbitopathy (GO) in in vitro model." (PMID 36521376, 2022). "We investigated the therapeutic effect of ibrutinib, an orally bioavailable BTK/ITK inhibitor, in a mouse model of Graves’ orbitopathy (GO)." (PMID 39280007, 2024).
head and neck cancer (2 papers, 2023 to 2024). A primary or metastatic malignant neoplasm affecting the head and neck. "However, since 83.4% of metastatic head and neck cancer tissues show a strikingly high abundance of BTK-p65, this specific isoform seems to be linked to metastatic processes." (PMID 37685940, 2023).
Hodgkins lymphoma (2 papers, 2023 to 2025). A heterogeneous group of malignant lymphoid neoplasms of B-cell origin characterized histologically by the presence of Hodgkin and Reed-Sternberg (HRS) cells in the vast majority of cases. "Ibrutinib is an FDA-approved irreversible bruton’s tyrosine kinase (BTK) inhibitor used to treat CLL and MCL, and clinical trials of ibrutinib are undergoing for classic Hodgkin’s lymphoma (CHL) (NCT02940301) and DLBCL (NCT03399513)." (PMID 36830087, 2023). "Moreover, calpain inhibition (calpain inhibitor II or CPI-2) also induces apoptosis among acute lymphoid leukemia (ALL) and non-Hodgkin’s lymphoma B cells, which is dependent on caspase activation but not on the protein tyrosine kinases LYN or Bruton’s tyrosine kinase (BTK)." (PMID 41294867, 2025).
IgA nephropathy (2 papers, 2021 to 2022). "This study demonstrated that macrophage BTK is involved in the development and progression of IgA nephropathy, but it still has certain limitations." (PMID 33389462, 2021). "In this study, renal biopsy tissues and blood samples from 63 patients were used to systematically analyze the expression of macrophage BTK in IgA nephropathy." (PMID 33389462, 2021). "BTK may be an important target in the pathogenesis of IgA nephropathy and is expected to be applied in clinical practice." (PMID 33389462, 2021). "However, the role of BTK in IgA nephropathy (IgAN) has not yet been elucidated." (PMID 33389462, 2021).
Insulin resistance (2 papers, 2019 to 2020). Increased resistance towards insulin, that is, diminished effectiveness of insulin in reducing blood glucose levels. "BTK has been implicated in pro‐inflammatory signalling; therefore, inhibiting BTK in infiltrating monocytes/macrophages could protect against the development of insulin resistance, through reduced production of soluble inflammatory mediators." (PMID 32608058, 2020).
interstitial lung disease (2 papers, 2021 to 2023). A diverse group of lung diseases that affect the lung parenchyma. "However, SY-1530 alleviates these adverse effects, including bleeding and interstitial lung disease, possibly because of its high BTK specificity." (PMID 34264564, 2021).
lymph node metastases (2 papers, 2020 to 2021). "High BTK expression was associated with poor tumor differentiation, advanced pathologic stage, lymph node metastasis, and large maximum tumor size." (PMID 34315851, 2021). "In lymph node metastases BTK expression was found in 23/32 of the cases (71.88%)." (PMID 32912025, 2020).
lymphoid neoplasm (2 papers, 2021 to 2022). A neoplasm composed of a lymphocytic cell population which is usually malignant (clonal) by molecular genetic and/or immunophenotypic analysis. "Constitutive activation of LYN and SYK has been shown to promote BTK-independent activation of the BCR cascade in ibrutinib-resistant lymphoid tumors." (PMID 35296646, 2022). "Under the influence of BTK inhibition by targeted drugs, CLL cells and malignant B-cells in other lymphoid neoplasms may adapt and compensate for the blocked BTK axis by activating the PI3K/Akt/Erk pathway." (PMID 33809580, 2021).
Muckle-Wells syndrome (2 papers, 2017 to 2020). "BTK is associated with NLRP3 and ASC and promotes ASC speck formation and caspase-1 cleavage, with the BTK inhibitor ibrutinib shown to be effective in blocking IL-1β secretion in immune cells derived from Muckle-Wells syndrome patients." (PMID 33603747, 2020). "Excessive IL-1β release in PBMC from Muckle-Wells Syndrome MWS (OMIM entry 191900) patients could also be blocked by BTK inhibitors." (PMID 29167667, 2017).
Myalgia (2 papers, 2023 to 2025). "Other TEAEs of interest for BTK inhibitors were headache (n = 10 [16.7%]), diarrhea (n = 9 [15.0%]), myalgia (n = 2 [3.3%]), and arthralgia (n = 1 [1.7%])." (PMID 39271521, 2025). "Rash, diarrhea, headache, nausea, fatigue, and myalgia have been reported for other second-generation BTK inhibitors." (PMID 36576659, 2023).
oral squamous cell carcinoma (2 papers, 2021 to 2023). "Recently, an aberrantly high expression of BTK was observed in specimens of oral squamous cell carcinoma (OSCC) patients together with reduced migration and invasion upon Ibrutinib treatment." (PMID 36612306, 2023).
osteoporosis (2 papers, 2021 to 2023). A condition of reduced bone mass, with decreased cortical thickness and a decrease in the number and size of the trabeculae of cancellous bone (but normal chemical composition), resulting in increased fracture incidence. "Since BTK plays a role in bone resorption and metabolism, our results suggest a need for further assessments on the potential occurrence of fractures and osteoporosis in patients treated with ibrutinib." (PMID 34776981, 2021).